EZH2 (enhancer of zeste 2 polycomb repressive complex 2 subunit)
Diseases named in the same sentence as EZH2 in open-access papers (continued):
Sharing a sentence is not in itself a finding about the gene and the disease.
tumor (continued). "Inhibitors of EZH2 (a component of PRC2) could attenuate the downstream effects of HOTAIR-mediated gene silencing, or lead to the de-repression of tumor-suppressive miRNAs like miR-34a in human pancreatic ductal adenocarcinoma, thereby initiating a cascade of anti-tumor and immunomodulatory effects." (PMID 41221298, 2025). "The treatment with 3 mM NaDCA did not affect EZH2 expression in the T98G tumor." (PMID 40725030, 2025). "Moreover, EZH2 and TOP2A are highly co-expressed in HCC tumor tissues, clinically." (PMID 40271060, 2025). "Interestingly, MSA-2 treatment did not decrease the primary tumor growth and metastatic potential in EZH2 KO cells compared to the WT." (PMID 38791429, 2024). "Here we show that combined inhibition of EZH2 and DOT1L HMTs with the small molecule inhibitors, SGC0946 and GSK343, synergistically drive a rapid ER stress response in NB cells, amino acid depletion, and reduced tumour growth in preclinical models suggesting a novel therapeutic strategy for NB." (PMID 39501501, 2024). "When CDK2 and EZH2 was recovered in POU4F1‐KO BLBC cells, ERα was re‐expressed and the downstream signaling was re‐activated, resulting in the conversion between basal‐like and luminal‐like phenotype, suggesting the regulatory role of cell cycle in tumor cell identity." (PMID 38491910, 2024). "However, both clinical and animal studies have shown that the anti-tumor effect of EZH2 inhibition therapy was significantly reduced in human or normal mice." (PMID 38243324, 2024). "It is intriguing to consider that precise timing of EZH2 inhibition could potentially enlarge reservoirs of stem-like CD8+ T cells, thereby fostering larger pools of effector cells, and consequently boosting both anti-tumor and anti-viral immunity." (PMID 38534385, 2024). "Lower EZH2 expression was found to be characteristic of the tumors of young HNSCC patients as opposed to the general population (median EZH2 staining intensity: 1 vs. 1.5 respectively, p < 0.001; median fraction of EZH2 positive tumor cells: 40% vs. 60%, respectively, p = 0.003, Mann–Whitney)." (PMID 38791289, 2024). "Additionally, tumor EZH2 levels exhibited a negative correlation with tumor-infiltrating CD8+ T cells and were associated with a poorer patient prognosis." (PMID 39080807, 2024). "EZH2 expression was found to be higher in HNSCC tumor cells than in corresponding non-tumoral regions, suggesting that an increased number of EZH2-positive cells might reflect increased cell proliferative activity." (PMID 38791289, 2024). "Of concern is that prior understanding of EZH2’s function has been primarily derived from 2D cell cultures, which fail to recapitulate the tumor microenvironment (TME), namely lacking cell-cell and cell-matrix interactions, nutrient/O2 gradients, and other TME-related stresses." (PMID 37992808, 2024). "One may also envision investigating systemic treatment with candidate EZH2 inhibitors, although our study highlighted that tumor-intrinsic, rather than the global inhibition of this pathway, may be beneficial." (PMID 38791429, 2024). "In addition, EZH2 also promotes the transition of TAMs to the M2 phenotype and inhibits the Th1-type chemokine C-X-C Motif Chemokine Ligand 9 (CXCL9) to reduce CD8+ T cell infiltration, thereby reducing the anti-tumor immune response." (PMID 39227959, 2024). "The enhancer of zest homolog 2 (EZH2), a family member of the histone methyltransferases (HMT), can promote the cancer development through the catalyzation of the trimethylation of lysine at position 27 of histone H3, resulting in the suppression of downstream tumor suppressor genes." (PMID 39149564, 2024). "Consequently, EZH2 may regulate HNSCC cell invasion and tumor glycolysis through the activation of STAT3." (PMID 38600608, 2024). "Additionally, we observed a significant negative correlation between EZH2 expression and PD‐L1 levels in the tumor microenvironment (TME)." (PMID 38520088, 2024).
tumor (continued). "The paradoxical effect of tumor-intrinsic EZH2 knockout on infiltrated neutrophils (decrease) as well as CD4+ and CD8+ T cells (increase) was even more striking when expressed as ratios, revealing a >20-fold decrease in the neutrophil:CD8+ T-cell ratio in EZH2 KO vs. WT and EZH2 OE tumors." (PMID 38791429, 2024). "Previous reports demonstrated some factors, such as Neuropilin-1 (NRP1) and enhancer of zeste homolog 2 (EZH2), restrictively deleted in Tregs impaired the transcription activity of FOXP3, restricting Treg-suppressive ability and conferring resistance to tumor growth in the host." (PMID 39446493, 2024). "It has been reported that EZH2 depletion mediates histone H3K27 trimethylation and reduces the enrichment of DNMT1 on the miR-200b/a/429 promoter, thus abolishing transcriptional silencing of miRNAs and suppressing tumor growth in gastric cancer and glioblastoma." (PMID 38890707, 2024). "Because the in vivo growth of tumor cells occurs at longer intervals and also involves other factors (e.g., immune cells), the in vitro data on EZH2 OE and KO 4T1 cells may not be predictive of their growth and metastatic potential in animals." (PMID 38791429, 2024). "On the other hand, the sustained high levels of serum EZH2 after surgery could be attributed to residual tumor cells still circulating in the blood stream, which have not been fully eradicated by the immune system or chemotherapy treatments." (PMID 38476362, 2024). "Decreased PD‐L1 expression in the tumor environment after USP22 knockdown was found and the upregulation effects of PD‐L1 and USP22 induced by Taz or immunotherapy were also attenuated, which suggested that USP22 is involved in EZH2‐mediated regulation of PD‐L1 expression." (PMID 38520088, 2024). "Disrupting the interaction between EZH2 and EED may be helpful to tumor inhibition." (PMID 38629070, 2024). "In a study evaluating the effectiveness of treating MLK-1 xenograft tumors in a mouse xenograft model with Tazemetostat—an EZH2 inhibitor—for 50 days, showed a significant attenuation of tumor growth by day 19 of treatment; however, a complete cessation of tumor growth was not achieved." (PMID 39456853, 2024). "Moreover, the specific components within the tumor microenvironment that contribute to the divergent biological behavior mediated by EZH2/PRC2 in HNSCC compared to other solid tumors are not yet identified." (PMID 38600608, 2024). "Given the role of EZH2 in modulating myogenic differentiation and promoting carcinogenesis, targeting EZH2 has emerged as a promising strategy in RMS treatment and in broader cancer therapy, potentially offering a new avenue to combat drug resistance and tumor recurrence." (PMID 39594601, 2024). "The enhanced interaction between T372-phosphorylated EZH2 and STAT3 reduced STAT3 phosphorylation, downregulating interleukin 6 receptor expression and inhibiting the cell proliferation and migration of epithelial ovarian cancer cells in vitro and decreasing ovarian xenograft tumor growth in vivo." (PMID 39769907, 2024). "Combined inhibition of EZH2 and DNMT1 augmented the expression of the inflammatory chemokines CXCL9 and CXCL10, which increased TILs and decreased tumor progression, thus improving the therapeutic efficacy of PD-L1 checkpoint blockade and adoptive T-cell transfusion in tumor-bearing mice." (PMID 37198402, 2023). "Moreover, EZH2-mediated H3K27me3 induces the silencing of the IL-15R, CD122, and NKG2D receptor proteins, hence suppressing NK-cell expansion and decreasing the cytotoxic targeting of tumor cells." (PMID 36766706, 2023). "Lily Keane’s team proposed the notion that inhibition of EZH2 in tumor cells could not have a practical effect, whereas inhibition of EZH2 in microglia may have a beneficial effect." (PMID 37700840, 2023).
tumor (continued). "Moreover, transcriptomic analysis of tumor-specific T cells in early malignant lesions revealed upregulation of DNA and histone modifying enzymes, including DNMT1, DNMT3B, EZH2, among others, indicating early involvement of the epigenetic machinery in driving the dysfunctional state." (PMID 36627707, 2023). "For instance, enhancer of zeste homolog 2 (EZH2), which is a well-known histone-lysine N-methyltransferase enzyme, was found highly expressed in a variety of cancers, and a selective inhibitor such as tazemetostat that block EZH2 activity was shown to exert profound anti-tumor effects." (PMID 36604642, 2023). "An epigenetic regulator gene with documented oncogenic function in ENKTL is EZH2, a histone methyltransferase that is not mutated in ENKTL but rather is aberrantly overexpressed and promotes NK tumor cell growth independently of its histone methyltransferase activity." (PMID 36900160, 2023). "Besides, EZH2 activity resulting from posttranslational phosphorylation at the serine-21 site is responsible for the increased enrichment of H3K27me3 at the RECK promoter region, which is related to tumor metastasis and angiogenesis." (PMID 37803297, 2023). "Thus, an exhaustive simplified model would suggest that EZH2 could act an oncogene, while KDM6A/UTX could bact as a tumor suppressor." (PMID 36968588, 2023). "The PRC2 complex is composed of several subunits (EZH2, EED, SUZ12, JARID2 and Rbap46.48), which are often amplified in MB, and their actions leads to an elevated level of H3K27me3 by repressing specific tumor suppressor genes, thus facilitating tumor development." (PMID 36968588, 2023). "Likewise, EZH2 and HDAC inhibitors are available and might be able to counter other epigenetic mechanisms of silencing or dysregulating antigen processing in tumor cells." (PMID 36555876, 2022). "In addition to MYC, EZH2 was previously shown to promote the expression of NF-κB targets and tumor cell growth independent of its histone methyltransferase activity in ER-negative basal-like breast cancer." (PMID 35013218, 2022). "Indeed, it has been reported that EZH2 phosphorylation by CDK2 at threonine 416 (T416) correlates with poor prognosis in triple-negative breast cancer (TNBC) and promotes cell migration and invasion, as well as tumor formation." (PMID 36135315, 2022). "As well, on the side of TAMs that are educated by EZH2 inhibitor-treated BC cells, the increased IL-10 secretion stimulates EGFR-SRC signaling to enhance cell motility and the increased VEGF secretion accelerates vasculature development, which contribute to tumor metastasis all together." (PMID 36038549, 2022). "Since EZH2 promotes the formation of CCF and subsequently the production of inflammatory factors, inflammatory factors may promote metastasis by remodeling the pre-metastatic environment of the tumor into a pro-tumor environment." (PMID 35163710, 2022). "However, EZH2 knockdown with or without PRADX overexpression in tumor cells revealed increased levels of BLCAP and reduced nuclear levels of p-STAT3." (PMID 35574370, 2022). "Recently, it has been proposed that EZH2 can influence lymphocyte subpopulation differentiation and function to reshape the TME, and thus inhibition of EZH2 may be a novel strategy to improve anti-tumor immunity in certain cancers." (PMID 36685594, 2022). "EZH2 inhibition using a selective chemical inhibitor GSK503, which targets the enzymatic activity of EZH2, significantly reduced the accumulation of H3K27me3 at tumor suppressor gene promoter regions, which lead to a significant decrease in tumor cells proliferation." (PMID 36230787, 2022).
tumor (continued). "Emerging researches suggest that EZH2 functions as a multifaceted molecule which exerts its canonical role in transcriptional silencing as a histone methyltransferase or activates genes that promote oncogenesis, tumor growth and metastasis independent of PRC2." (PMID 36038549, 2022). "Furthermore, EZH2 was capable of modulating several tumor processes like cell cycle, proliferation, apoptosis, invasion, and mobility, GBM stem cell differentiation and maintenance, and tumor angiogenesis." (PMID 35419058, 2022). "The main body of data indicates that the KDM6A/UTX demethylase protein acts as a tumour suppressor, and that tumours lacking or carrying mutations in KDM6A may, in some cancers, be targeted with either EZH2 or BET inhibitors." (PMID 35406676, 2022). "According to previous research, EZH2 upregulation was associated with HCC progression and multiple HCC metastatic features, including venous invasion, direct liver invasion, and the absence of tumor encapsulation." (PMID 35208478, 2022). "Previous studies have focused on discovering EZH2 inhibitors for targeted therapy, however, our study provided a novel therapeutic avenue for developing an effective inhibitor to disrupt PRADX-EZH2 interaction, thus increasing the expression of TSGs and finally inhibiting tumor growth." (PMID 35574370, 2022). "Expression levels of NEAT1 and GAS5 were also significantly increased in tumor samples compared with adjacent normal tissue (p-value = 2.16e−8 for GAS5 and p-value = 0.01 for NEAT1, t-test), suggesting that they inhibit apoptosis in HCC, perhaps by interacting with EZH2 and JARID2." (PMID 36578923, 2022). "Furthermore, to explore whether the EZH2 inhibition has a synergistic effect with checkpoint blockade therapy, we injected the anti-mouse PD1 antibody into the EZH2 knockdown tumor model." (PMID 35912007, 2022). "In accordance with this hypothesis of ours, PC3RR expresses higher EZH2, a factor recently shown to be involved in secondary metastatic spread from the microenvironment, rather than in tumour growth." (PMID 36428597, 2022). "In addition, EZH2 also plays a critical role in anti-senescence programs in both non-tumor cells and tumor cells." (PMID 36009484, 2022). "In addition, EZH2 re-expressing 231.KO#1.EZH2 cells with or without GSK126 treatment showed similarly increased tumor cell proliferation and osteoclast maturation compared to 231.KO#1.pLenti cells." (PMID 35538070, 2022). "The synergistic effect of olefin and gefitinib on NSCLC cells depends in part on the downregulation of EZH2, an H3K27 methyltransferase recognized as a gene transcription regulator and cancer driver primarily through its epigenetic and global ability to modify tumor-related genes." (PMID 34641334, 2021). "Epigenetic related alterations such as inhibition of enhancer of zeste homology 2 (EZH2) and variations in lysine-specific demethylase 1A (LSD1) were also noted to play a role in tumor immunogenicity as well as response to treatment, and they provide promising anti-tumor targets." (PMID 34677265, 2021). "Additionally, the functional activation of METTL3 could promote rapid tumor growth and EMT, which dependent of the activation of PI3K/AKT pathways and the overexpression of EZH2." (PMID 33879256, 2021). "Pharmacological inhibition of EZH2 enhanced MDSC generation in both tumor and non-tumor models." (PMID 34737746, 2021). "The Deazaneplanocin A (DZNep), an EZH2 inhibitor, was tested along with the small-molecule compound AC1Q3QWB (AQB) in vitro, as well as in orthotopic breast cancer and GBM patient-derived xenograft (PDX) models, and was demonstrated to significantly reduce tumor growth." (PMID 33430434, 2021). "However, there is still no pan-cancer evidence on the relationship between EZH2 and various tumor types based on big clinical data." (PMID 34381492, 2021).
tumor (continued). "However, the tumour inhibition by infigratinib and varlitinib in EZH2-overexpressing HCC21-0208 was not complete, which was presumably due to the activation of both the FGFR and ErbB pathways." (PMID 34156519, 2021). "Interestingly, impairment of EZH2 activity did not reduce the proliferation of the tumor cells as it was observed for numerous other BC cell lines in the past." (PMID 34845197, 2021). "Notably, EZH2 expression correlated with increased tumor invasion and higher grade, but not with lymph node status." (PMID 34175897, 2021). "This may reflect such an early transformation event that EZH2 is no longer required for tumour cell growth beyond the in situ stage and therefore redundant in terms cell oncological dependence." (PMID 33937922, 2021). "Moreover, focus must shift towards slowly eradicating cycling tumor-initiating cells that are resistant to cytotoxic drugs and inhibitors, such as those expressing SOX2+ or high H3K27 methylation and EZH2 expression, and can eventually give rise to recurrent tumors recalcitrant to treatment." (PMID 35054230, 2021). "However, studies on how autophagy induction by EZH2 inhibitors affected overall tumor growth inhibition remain lacking." (PMID 34440583, 2021). "Similarly, EZH2 inhibition in OAC may potentiate Treg recruitment of effector T-cells and NK cell maturation to increase this anti-tumour response as seen in other cancer types." (PMID 34439236, 2021). "Disruption of EZH2 activity in Treg cells via either genetic or pharmacologic means led to the acquisition of pro-inflammatory functions in tumor-infiltrating Treg cells, the remodeling the TME and enhanced recruitment and function of CD8+ and CD4+ effector T cells, leading to tumor elimination." (PMID 34930302, 2021). "When EZH2 is absent or inhibited in regulatory T cells, their ability to suppress effector T cells was blocked, increasing intratumoral levels of effector T cells, and reducing tumor growth." (PMID 34604225, 2021). "Moreover, temporal genetic deletion of Ezh2 in Tregs showed better control of implanted murine prostate TRAMPC2 and colon adenocarcinoma MC38 tumor growth without causing auto-immune toxicities." (PMID 33403469, 2021). "Studies have shown that EZH2 can inhibit the expression of tumor suppressor genes in normal cells, thereby promoting the abnormal proliferation of cells, and stimulating the metastasis of tumor cells." (PMID 33679454, 2021). "Taken together, the tumor-suppressive activity of miR-449a in NPC cells might be attributed to the inhibition of expression of multiple cell growth regulators, such as LDHA and EZH2." (PMID 32752071, 2020). "EZH2 is a negative independent prognostic factor and exhibits tumor promoting activity in GBM." (PMID 32373523, 2020). "A battery of 10 SCLC cell lines were grown as 3D tumor spheroids and treated with eight small molecule inhibitors, two for each target, in order to assess the efficacy of BET or Aurora Kinase inhibition in combination with EZH2 or PARP-1 inhibition on SCLC cells." (PMID 33339368, 2020). "In the CAMK2A-EZH2-SOX2 pathway, CAMK2A is the only factor specifically expressed in tumor but not normal lung, and thus might be a relatively safe treatment target compared with non-specifically inhibiting EZH2 and SOX2." (PMID 32483123, 2020).